RFLNB (refilin B)
Description:
Involved in the regulation of the perinuclear actin network and nuclear shape through interaction with filamins. Plays an essential role in the formation of cartilaginous skeletal elements.
Synonyms: RefilinB; MGC45871; Cfm1; FAM101B
Tractability: Antibody: the Human Protein Atlas places it where antibodies can reach.
Gene: Protein-coding gene on chromosome 17 (439,978 to 445,939, reverse strand). Ensembl gene ENSG00000183688.
Subcellular location: Cytoplasm, cytoskeleton
Subcellular location (Human Protein Atlas): Actin filaments; Cytosol; Plasma membrane
Gene Ontology:
Molecular function: filamin binding
Biological process: actin filament bundle organization; negative regulation of bone mineralization involved in bone maturation; negative regulation of chondrocyte development; skeletal system morphogenesis; regulation of chondrocyte development
Cellular component: actin cytoskeleton; actin filament bundle; cytoskeleton
Genetic constraint (gnomAD): Loss-of-function variants: 6 observed, 9.17 expected, observed/expected ratio (o/e) 0.65, 90% interval 0.36 to 1.29. That is too few expected variants to judge how well the gene tolerates losing a copy. Missense variants: 171 observed, 181.81 expected, observed/expected ratio (o/e) 0.94, 90% interval 0.83 to 1.07. Synonymous variants: 91 observed, 84.09 expected, observed/expected ratio (o/e) 1.08, 90% interval 0.91 to 1.29.
Homologues: Orthologues: chimpanzee RFLNB (97% identical), macaque RFLNB (90% identical), rabbit RFLNB (88% identical), dog RFLNB (85% identical), pig RFLNB (85% identical), guinea pig RFLNB (83% identical), mouse Rflnb (83% identical), rat Rflnb (78% identical), tropical clawed frog rflnb (65% identical), zebrafish rflnb (48% identical). Paralogues in human: RFLNA (36% identical).
Diseases named in the same sentence as RFLNB in open-access papers:
RFLNB is named in the same sentence as 19 diseases in open-access papers, as found by Europe PMC text mining. Sharing a sentence is not in itself a finding about the gene and the disease. The quoted sentences say what the papers report.
neuroblastoma (2 papers, 2017 to 2024). Neuroblastoma (NB) is the most common solid, extracranial childhood tumor. "Refilin b (RFLNB) is responsible for the epithelial–mesenchymal transition (EMT) and inhibits tumoral growth in neuroblastoma and pleural malignant mesothelioma." (PMID 38673800, 2024).
tumor (8 papers, 2017 to 2024). "So far, no studies have shown that these seven genes (IGHG2, PODXL2, LRRC17, GABRA3, SCUBE3, HLF and RFLNB) are directly related to pyroptosis in tumor cells." (PMID 36155774, 2022). "The results showed that compared with HSKMC, PODXL2, LRRC17, GABRA3, SCUBE3, and RFLNB were highly expressed in tumor cells, while IGHG2 and HLF were low expressed." (PMID 36155774, 2022). "Another identified interactor of RFLNB/FAM101B was WDFY4, which plays a critical role in the regulation of classical dendritic cells mediated cross-presentation of viral and tumor antigens." (PMID 37798266, 2023). "The impairment or attenuation of miRNAs could potentially stabilize RFLNB and INSR expression, promoting tumor growth." (PMID 38673800, 2024).
RFLNB also shares sentences with these, for which no sentence is quoted: prostate carcinoma (3 papers); cancer (2); cystic fibrosis (2); metastatic disease (2); prostate tumor (2); choriocarcinoma (1); endometrial adenocarcinoma (1); epidermoid carcinoma (1); glioma (1); infection (1); leukemia (1); lymphoma (1); Meconium ileus (1); melanoma (1); pleural malignant mesothelioma (1); sarcoma (1); viral infection (1).